SIRT3 (sirtuin 3)
Description:
NAD-dependent protein deacetylase. Activates or deactivates mitochondrial target proteins by deacetylating key lysine residues. Known targets include ACSS1, IDH, GDH, SOD2, PDHA1, LCAD, SDHA, MRPL12 and the ATP synthase subunit ATP5PO. Contributes to the regulation of the cellular energy metabolism. Important for regulating tissue-specific ATP levels. In response to metabolic stress, deacetylates transcription factor FOXO3 and recruits FOXO3 and mitochondrial RNA polymerase POLRMT to mtDNA to promote mtDNA transcription. Acts as a regulator of ceramide metabolism by mediating deacetylation of ceramide synthases CERS1, CERS2 and CERS6, thereby increasing their activity and promoting mitochondrial ceramide accumulation (By similarity). Regulates hepatic lipogenesis (By similarity). Uses NAD(+) substrate imported by SLC25A47, triggering downstream activation of PRKAA1/AMPK-alpha signaling cascade that ultimately downregulates sterol regulatory element-binding protein (SREBP) transcriptional activities and ATP-consuming lipogenesis to restore cellular energy balance (By similarity). In addition to protein deacetylase activity, also acts as a protein-lysine deacylase by recognizing other acyl groups, such as benzoyl and lactoyl, leading to protein debenzoylation and delactylation, respectively. Catalyzes debenzoylation of PPIF and ACLY. Mediates delactylation of CCNE2 and 'Lys-16' of histone H4 (H4K16la).
Synonyms: SIR2L3
Tractability: Small molecule: a structure with a bound ligand is known; a high-quality ligand is known; it has a high-quality binding pocket; it belongs to a druggable protein family. PROTAC: its protein half-life has been measured; a small molecule that binds it is known.
Target class: Histone deacetylase; HDAC class III; Epigenetic regulator; Eraser
Gene: Protein-coding gene on chromosome 11 (215,028 to 236,931, reverse strand). Ensembl gene ENSG00000142082.
Subcellular location: Mitochondrion matrix
Pathways (Reactome):
Gene expression (Transcription): FOXO-mediated transcription of oxidative stress, metabolic and neuronal genes; Regulation of FOXO transcriptional activity by acetylation
Cellular responses to stimuli: Mitochondrial unfolded protein response (UPRmt)
Metabolism: Maturation of TCA enzymes and regulation of TCA cycle
Organelle biogenesis and maintenance: Transcriptional activation of mitochondrial biogenesis
Gene Ontology:
Molecular function: NAD-dependent protein lysine deacetylase activity; NAD-dependent protein lysine delactylase activity; protein binding; sequence-specific DNA binding; zinc ion binding; histone deacetylase activity, NAD-dependent; NAD+ poly-ADP-ribosyltransferase activity; NAD+-protein mono-ADP-ribosyltransferase activity; protein lysine deacetylase activity; acyltransferase activity, transferring groups other than amino-acyl groups; enzyme binding; NAD+ binding
Biological process: aerobic respiration; mitochondrial fusion; peptidyl-lysine deacetylation; positive regulation of catalase activity; positive regulation of oxidative phosphorylation; positive regulation of superoxide dismutase activity; protein deacetylation; cellular response to stress; positive regulation of ceramide biosynthetic process; chromatin remodeling; negative regulation of ERK1 and ERK2 cascade; negative regulation of reactive oxygen species metabolic process; positive regulation of insulin secretion
Cellular component: mitochondrial matrix; mitochondrion; protein-containing complex; nucleoplasm
Genetic constraint (gnomAD): Loss-of-function variants: 24 observed, 28.78 expected, observed/expected ratio (o/e) 0.83, 90% interval 0.6 to 1.17. The upper end of that interval is the gene's LOEUF score, 1.17, which puts it in group 5 of 6, group 1 being the genes least tolerant of losing a copy. Missense variants: 578 observed, 491.02 expected, observed/expected ratio (o/e) 1.18, 90% interval 1.1 to 1.26. Synonymous variants: 237 observed, 205.01 expected, observed/expected ratio (o/e) 1.16, 90% interval 1.04 to 1.29.
Homologues: Orthologues: chimpanzee SIRT3 (98% identical), macaque SIRT3 (93% identical), rabbit SIRT3 (67% identical), pig SIRT3 (66% identical), rat Sirt3 (65% identical), dog SIRT3 (64% identical), guinea pig SIRT3 (55% identical), mouse Sirt3 (55% identical), zebrafish sirt3 (50% identical), tropical clawed frog SIRT3 (39% identical). Paralogues in human: SIRT2 (38% identical), SIRT1 (31% identical), SIRT4 (19% identical), SIRT7 (19% identical), SIRT5 (19% identical), SIRT6 (18% identical).
Diseases named in the same sentence as SIRT3 in open-access papers:
SIRT3 is named in the same sentence as 361 diseases in open-access papers, as found by Europe PMC text mining. Sharing a sentence is not in itself a finding about the gene and the disease. The quoted sentences say what the papers report.
cardiac hypertrophy (166 papers, 2010 to 2026). "Reactive oxygen species (ROS) and oligomycin sensitivity-conferring proteins (OSCP) are associated with the acetylation of SIRT3 substrates, and both are key regulators of cardiac hypertrophy." (PMID 40710369, 2025). "In preclinical models, SIRT3 overexpression significantly mitigates cardiac hypertrophy and fibrosis, whereas SIRT3 deficiency promotes the development of hypertrophic cardiomyopathy and progressive ventricular dysfunction." (PMID 40860195, 2025). "FTZ has the potential to mitigate HF caused by pressure-induced cardiac hypertrophy by inactivating the miR-214/SIRT3 signaling pathway." (PMID 39564110, 2024). "An earlier study in 2024 also noted that canagliflozin alleviates cardiac hypertrophy in mice caused by high salt intake, which suppresses SIRT3 expression in the heart." (PMID 39539627, 2024). "With age, SIRT3-deficient mice spontaneously develop cardiac hypertrophy, and they are more susceptible to hypertrophic responses induced by TAC, Ang II, or isoprenaline infusion than WT mice." (PMID 37237500, 2023). "Accumulating evidence has shown that Sirt3 can relieve injury due to metabolic stress, tumours, the development of cardiac hypertrophy and age‐related hearing loss by reducing mitochondrial damage and ROS production." (PMID 36433732, 2023). "A wealth of evidence suggests that the downregulation of SIRT3 represents a causative factor in cardiac hypertrophy and fibrosis, followed by heart failure." (PMID 37371077, 2023). "In this regard, studies have shown that Sirt3-deficient mice have signs of cardiac hypertrophy and cardiac abnormalities due to defective trans-mitochondrial cristae alignment and impaired mitochondrial bioenergetics." (PMID 36675125, 2023). "Activation of SIRT3 has been also implicated in lessening the severity of cardiac hypertrophy by blocking interstitial fibrosis, as well as fibroblast proliferation and differentiation." (PMID 34409084, 2021). "Increased mitochondrial ROS due to Sirt3 deficiency is closely associated with many cardiovascular diseases, such as cardiac hypertrophy, myocardial fibrosis, and heart failure." (PMID 34095262, 2021). "In line with a previous study, SIRT3 deficiency leads to an increased acetylation of mitochondrial metabolic proteins, which induces cardiac hypertrophy and accelerates obesity-induced heart failure." (PMID 34829803, 2021). "Reduced activity of PDH in association with its increased acetylation and decreased SIRT3 level has been also demonstrated in mice with angiotensin II-induced cardiac hypertrophy." (PMID 34409084, 2021). "SIRT3 can protect the heart from multiple types of diseases which cause cardiac hypertrophy and fibrosis, through the regulation of oxidative stress, metabolism and aging." (PMID 34180125, 2021). "By deacetylating cyclophilin D, a regulator of the mitochondrial permeability transition pore, SIRT3 prevents age-associated increases in mitochondrial permeability and swelling, cardiac hypertrophy and fibrosis." (PMID 34829803, 2021). "Pathological hypertrophic stimuli caused cardiac hypertrophy and fibrosis and reduced the expression levels of Sirt3 and MnSOD." (PMID 33014281, 2020). "A study also reported that Sirt3-deficient mice developed dilated cardiomyopathy, and Sirt3 knockout mice exacerbated angiotensin II-induced cardiac hypertrophy." (PMID 33014281, 2020). "Many studies have revealed that Sirt3 is closely associated with the pathogenesis of cardiac diseases, particularly cardiac hypertrophy." (PMID 33233476, 2020). "Sirt-3 deficient mice demonstrate mitochondrial dysfunction and excessive production of ROS as well cardiac fibrosis and hypertrophy." (PMID 32116760, 2020). "An increasing number of studies revealed that poor SIRT3 activity is one of the causes of cardiac hypertrophy and heart failure." (PMID 29643974, 2018). "Mice with SIRT3 deficiency display signs of cardiac hypertrophy and interstitial fibrosis by 8 weeks of age." (PMID 30131726, 2018).
cardiac hypertrophy (continued). "In the presence of heart hypertrophy, Sirt3 results overexpressed causing an increase of MAPK/ERK, PI3K/Akt and Ras pathway activity, as well as an intracellular increase in ROS levels." (PMID 30304806, 2018). "Studies on SIRT3 deficient mice revealed that SIRT3 plays a cardioprotective role in cardiac hypertrophy by suppressing ROS production through the induction of FOXO3a." (PMID 30131726, 2018). "Attenuation of cardiac hypertrophy by SIRT3 was associated with deacetylation and nuclear translocation of FoxO3 whereby it stimulated transcription of antioxidant enzymes." (PMID 28559847, 2017). "Protein acetylation is an important regulator of cardiac metabolism and loss of SIRT3 increases susceptibility of the heart to stress-induced cardiac hypertrophy and ischemic injury." (PMID 28542596, 2017). "In numerous settings including embryonic development, age-related hearing loss, neuronal injury, and cardiac hypertrophy, Sirt3 has been shown to protect from oxidative stress." (PMID 27071400, 2016). "Loss of function studies demonstrated a role of impaired SIRT3 activity in the pathogenesis of myocardial IR injury as well as in the development of cardiac hypertrophy and the transition into heart failure." (PMID 27790619, 2016). "Increasing evidence suggests a causative role of impaired SIRT3 activity in a number of cardiac pathologies, including cardiac hypertrophy and heart failure." (PMID 27790619, 2016). "Though Sirt3-deficient mice didn't show visible phenotypes, they developed evident myocardial hypertrophy and interstitial fibrosis at eight weeks of age." (PMID 27880725, 2016). "High-fat diet caused comparable increases in heart weight and cardiac hypertrophy, as indexed by the heart weight to tibia length ratio, in both WT and SIRT3 KO mice." (PMID 25782072, 2015). "Sirtuin 3 is involved in aging and cardiac homeostasis, and its overexpression is protective against cardiac hypertrophy while depletion enhances the susceptibility to hypertrophy." (PMID 25649709, 2015). "Cardiac hypertrophy is also associated with reduced free fatty acid oxidation and the SIRT3 levels are reduced in hypertrophic/failing hearts." (PMID 25748450, 2015). "In particular, SIRT1 and SIRT3 appear to share similar ROS-accumulating end-point targets that cause cardiac hypertrophy." (PMID 24265619, 2013). "Although SIRT3 deficient mice appear to have normal activity, they show signs of cardiac hypertrophy at 8 weeks of age." (PMID 24073959, 2013). "SIRT3-deficient mice show signs of cardiac hypertrophy andinterstitial fibrosis at 8 weeks of age, while SIRT3 transgenic overexpressingmice are protected from application of hypertrophic stimuli." (PMID 20375467, 2010). "SIRT1 and SIRT3 appear to share similarROS-accumulating end-point targets that cause cardiac hypertrophy." (PMID 20375467, 2010). "Evidence from experimental and clinical studies has shown that hypertension-induced decreases in SIRT3 activity can lead to cellular metabolism reprogramming and, subsequently, increased susceptibility to endothelial dysfunction, myocardial hypertrophy, myocardial fibrosis, and heart failure." (PMID 37237500, 2023). "Therefore, our data provide further evidence of a biological link underlying the association between NDUFC2, SIRT3 and cardiac hypertrophy." (PMID 37558995, 2023). "Significantly enhances SIRT3 signal expression; alleviates oxidative stress injury of myocardial tissue; inhibits the progression of myocardial fibrosis; and improves pathological myocardial hypertrophy caused by stress load." (PMID 35566359, 2022). "Hence, we focused on the Sirt3/SOD2 signaling pathway in order to elucidate the possible mechanisms underlying the inhibitory effects of SA against cardiac hypertrophy." (PMID 33233476, 2020).
cardiac hypertrophy (continued). "Also, it has been elaborated that Sirt3 deficiency exacerbates cardiac hypertrophy and heart failure in transverse aortic constriction mice, whereas Sirt3 overexpression protects against maladaptive ventricular remodeling." (PMID 33014281, 2020). "In conclusion, the study suggested that exogenous H2S supplement inhibited ISO-induced cardiac hypertrophy depending on SIRT3, and the possible mechanisms might be associated with antioxidant stress." (PMID 30647820, 2018). "Thus, SIRT3 acts as a negative regulator of cardiac hypertrophy and aging-associated tissue fibrosis." (PMID 30131726, 2018). "Our present study suggested that exogenous H2S supplement inhibited ISO-induced cardiac hypertrophy depending on SIRT3, which might be associated with antioxidant stress." (PMID 30647820, 2018). "Deficiency of SIRT3 is associated with increased susceptibility to develop cardiac hypertrophy." (PMID 28423723, 2017). "Importantly, they also demonstrated that NMN treatment attenuated isoproterenol-induced cardiac hypertrophy, a beneficial effect that was blunted in mice with additional SIRT3 deficiency." (PMID 27790619, 2016). "Anti-oxidative effects of Sirt3 have been described in a variety of contexts including age-related hearing loss, embryogenesis, neuronal injury, exercise training, and cardiac hypertrophy." (PMID 27071400, 2016). "Loss of SIRT3 has been related to cardiac hypertrophy in ageing 14,24." (PMID 25782072, 2015). "SIRT3-deficient mice have greatly decreased levels of tissue adenosine triphosphate (ATP), impaired cold tolerance when fasted, and more susceptibility to cardiac hypertrophy, breast cancer and high-fat diet-induced metabolic syndrome." (PMID 24454908, 2014). "SIRT3 overexpression blocks hypertrophy both in vitro and in vivo, whereas SIRT3−/− mice exhibit enhanced susceptibility to hypertrophy, though it is also likely that it indirectly protects against cardiac hypertrophy by specifically controlling ROS levels." (PMID 23774840, 2013). "SIRT3 overexpression blocks hypertrophy both in vitro and in vivo, whereas SIRT3−/− mice exhibit enhanced susceptibility to hypertrophy, likely indirectly protecting against cardiac hypertrophy by specifically control of ROS levels." (PMID 24265619, 2013). "Reduced levels of SIRT3 in human hearts are linked to hyperacetylation of mitochondrial proteins and disrupted energetic metabolism, leading to structural and functional alterations in the heart, ultimately contributing to cardiac hypertrophy and heart failure." (PMID 40352788, 2025). "SIRT3 has been reported to preserve mitochondrial function during ageing through the deacetylation of cyclophilin D (CypD) on lysine 166, and SIRT3-deficient mice showed accelerated signs of cardiac ageing such as cardiac hypertrophy and fibrosis at a young age and hypersensitivity to heart stress." (PMID 35821839, 2022). "In addition to cancer, SIRT3 also plays important functions in multiple age-associated diseases, including hearing loss, obesity, diabetes, insulin resistance, neurodegeneration, cardiac hypertrophy, liver steatosis, and glucose homeostasis disorders." (PMID 35571098, 2022). "In this direction, the mouse model of Sirt3 deficiency shows that the increase of mitochondrial transition pore permeability (mPTP) paralleled by a dysregulated TGFβ1 signaling is associated with cardiac hypertrophy and interstitial fibrosis detectable since early life stages." (PMID 30304806, 2018). "In this regard, loss of Sirt3 results in a series of stress and/or aging-related murine phenotypes including receptor positive breast cancer, fatty liver, insulin resistance, cardiac hypertrophy, radiation-induced liver steatosis, and age-associated hearing loss." (PMID 22016654, 2011).